TCF7L1 (transcription factor 7 like 1)
Diseases named in the same sentence as TCF7L1 in open-access papers (continued):
Sharing a sentence is not in itself a finding about the gene and the disease.
tumor (continued). "In addition to TCF7L1, Wnt genes are also commonly dysregulated in diverse tumor cells, including prostate, ovarian, colon, and skin cancers." (PMID 31438551, 2019). "Importantly, downregulating LCN2 decreased tumor size, abrogating the effect of TCF7L1 overexpression on tumor growth." (PMID 28467300, 2017). "Moreover, we demonstrate that TCF7L1 overexpression promotes tumor growth, enhances migration, and suppresses oncogenic RAS-induced senescence independently of β-catenin interaction." (PMID 28467300, 2017). "Since LCN2 has been shown to stimulate neutrophil chemotaxis in vitro, and inflammation facilitates tumor growth, we evaluated whether overexpressing TCF7L1 increases neutrophil infiltration in tumors and whether downregulating LCN2 alters their infiltration." (PMID 28467300, 2017). "However, our data demonstrate that TCF7L1 promotes tumor growth independently of its interaction with β-catenin, requiring only its binding to DNA and Groucho/TLE corepressors." (PMID 28467300, 2017). "Thus, as with its role in promoting tumor growth and suppressing oncogene-induced senescence, TCF7L1 stimulated migration of skin SCC cells independently of its interaction with β-catenin." (PMID 28467300, 2017). "Since downregulation of both TCF7L1 and TCF7L2 in SCC cells were required to reduce xenografted tumor growth, it suggested that TCF7L1 and TCF7L2 can compensate for each other and that they may have a similar function in skin SCC." (PMID 28467300, 2017). "Finally, we identified the secreted protein LCN2 as the downstream effector of TCF7L1 that stimulates tumor growth." (PMID 28467300, 2017). "Importantly, downregulation of TCF7L1 was shown to decrease tumor growth and reduce metastasis rate." (PMID 28467300, 2017). "To determine whether TCF7L1 overexpression alone was sufficient to promote tumor formation, we treated TCF7L1-induced mice with an acetone vehicle control instead of DMBA/TPA." (PMID 28467300, 2017). "Our work is the first to use deletion mutations of TCF7L1 to show that TCF7L1 does not require binding to β-catenin to promote tumor growth." (PMID 28467300, 2017). "To assess whether TCF7L1 overexpression in human SCC cells drives tumor growth, we next evaluated the effect of TCF7L1 overexpression in the xenograft model of human skin SCC." (PMID 28467300, 2017). "We hypothesized that TCF7L1 overexpression may help tumor cells overcome oncogene-induced senescence, which is a phenomenon observed both in vitro and in vivo." (PMID 28467300, 2017). "To determine whether TCF7L1 could substitute for TPA’s tumor-promoting role, we treated the TCF7L1-induced mice with an initial dose of DMBA (25 nmol) and an acetone vehicle control in place of TPA." (PMID 28467300, 2017). "Our results therefore indicate that TCF7L1 may have an as yet unidentified role in transmission of tumor-related β-Catenin signals." (PMID 21853123, 2011). "In leukemia, the knockdown of TCF7L1 could reduce tumor growth." (PMID 33824876, 2021). "The direct comparison between the AXIN2- and all TCF7L1 gene expression-correlated transcriptomes confirms the higher correlation of TCF7L1 expression with cell adhesion-associated transcripts, not just in normal tissue, but also in tumor tissue." (PMID 32403323, 2020). "Although these in vitro results suggest that this may be a mechanism by which TCF7L1 overexpression increases tumor incidence and growth, we currently lack the in vivo data to support this claim due to technical limitations associated with detecting senescent markers in mouse epidermis." (PMID 28467300, 2017). "Our results imply that TCF7L1 might act as a transcriptional repressor in its tumor-promoting role, further supporting the model that TCF7L1 functions primarily as a repressor and not as a WNT target gene-activating β-catenin cofactor as shown in a variety of developmental processes." (PMID 28467300, 2017).
tumor (continued). "For example, tumor cells showed particularly high expressions of KRT8, KRT18 and TCF7L1, whereas endothelial cells showed particularly high expressions of PECAM1 and VWF.." (PMID 35494058, 2022). "Second, the survival analysis showed that 7 genes had significant (p < 0.05) Kaplan–Meier curves, including 5 genes (MS4A1, N4BP2L1, IGF1R, TCF7L2 and COL11A1) based on the normal expression, and 2 genes (TCF7L1 and PTPRM) based on the tumor expression." (PMID 35406404, 2022). "Firstly, there is strong correlation of TCF7L1 with FZD7 expression, particularly in normal but also in tumor tissue." (PMID 32403323, 2020). "Among the R-spondin genes, RSPO2 expression is clearly correlated with TCF7L1, but only in normal tissue, while RSPO3 expression is less strongly correlated with TCF7L1, both in normal and tumor tissue." (PMID 32403323, 2020). "Our meta-analysis confirms that among the four human LEF/TCF genes, LEF1 and TCF7 are preferentially expressed in tumor biopsies, while TCF7L2 and TCF7L1 in normal control tissue." (PMID 32403323, 2020). "Comparison between these two, i.e. between TCF7L1- and LEF1-correlated transcription, also reveals a potential correlation of LEF1 expression with double strand break DNA repair in tumor." (PMID 32403323, 2020). "Apart from β-catenin, TCF7L1 (also known as TCF3), a binding partner for β-catenin, is known to contribute to tumor prevalence and progression in the pathogenesis of several cancers." (PMID 31438551, 2019). "Genes in the KEGG WNT signaling pathway, including Ccnd1/2/3, Myc and Tcf7l1, were down-regulated in the transcriptome of G3 MB tumorspheres overexpressing WDR11, consistent with reduced tumor progression." (PMID 29029386, 2017). "Conversely, overexpression of TCF7L1 increased tumorigenic capacity of SCC cells in limiting dilution assay and stimulated tumor growth." (PMID 28467300, 2017). "Consistent with the observation that silencing TCF7L1 and TCF7L2 reduced tumor size, their downregulation reduced SCC cell proliferation in vitro and in vivo." (PMID 28467300, 2017). "We found that knocking down TCF7L1 only modestly reduced tumor growth while knocking down both TCF7L1 and TCF7L2 significantly reduced the tumor size." (PMID 28467300, 2017). "However, TCF7L1, SCG3 and SV2C were the specifically expressed genes of tumor cell subtypes in primary tumor sites." (PMID 35494058, 2022). "To determine the tumorigenic role of TCF7L1 in PCa, we used a TMA obtained from the Department of Pathology at Duke University School of Medicine (Durham, NC, USA), which was comprised of normal and PCa-progressed tumor tissues." (PMID 34799554, 2021). "Mice that were administered subcutaneous injections of PC3 cells harboring TCF7L1-KD showed no changes in tumor growth rates or tumor weights compared to mice injected with cells carrying the NC shRNA." (PMID 34799554, 2021). "We first tested our hypothesis about differential expression of LEF/TCF genes between tumor and normal tissue with forest plots of all four LEF/TCF genes (TCF7, LEF1, TCF7L1, TCF7L2)." (PMID 32403323, 2020). "Importantly, among the LEF/TCF genes, our meta-analysis also corroborates a switch from relatively higher TCF7L2 and TCF7L1 expression in normal control to relatively higher TCF7 and LEF1 expression in tumor tissue." (PMID 32403323, 2020). "Furthermore, transcripts indicative of angiogenesis are correlated with TCF7L1 in tumor; and transcripts indicative of DNA double-strand break repair and of cell cycle progress with LEF1 in tumor." (PMID 32403323, 2020). "Positive correlations linking TCF7 with LEF1 and with LGR5 in normal tissue are reduced in tumor tissue, and the negative correlation between AXIN2 and TCF7L1 in normal tissue is also reduced in tumor tissue." (PMID 32403323, 2020). "Overexpression of TCF7L1 increased tumor incidence, promoted tumor growth, and enhanced migration independent of β-catenin." (PMID 31438551, 2019).
tumor (continued). "In the DMBA/TPA chemical carcinogenesis protocol, because the tumor-initiating step (DMBA) is distinct from the promoting step (TPA), we could identify which phase of tumorigenesis was impacted by TCF7L1 overexpression by omitting each agent." (PMID 28467300, 2017). "Additionally, we show that downregulation of TCF7L1 and its paralogue TCF7L2 reduces tumor growth in a xenograft model of human skin SCC." (PMID 28467300, 2017). "This is not surprising given that overexpression of TCF7L1 and TCF7L1ΔN produced a similar effect on tumor growth, OIS, and cell migration." (PMID 28467300, 2017). "In a xenograft model of human skin SCC, downregulation of TCF7L1 and its paralogue TCF7L2 decreased tumor size, indicating that these two LEF/TCF family members, whose functions overlap in skin development, are required for the optimal growth of xenografted tumors." (PMID 28467300, 2017). "Importantly, overexpression of TCF7L2 also increased xenografted SCC tumor size, accelerated cell migration, and counteracted HRASG12V-induced senescence similarly as TCF7L1." (PMID 28467300, 2017). "The paracrine effect of TCF7L1 on cell migration in vitro and wound closure in vivo suggested that the secreted LCN2 might be a prime effector of TCF7L1 in skin tumorigenesis." (PMID 28467300, 2017). "We identified a group of CTNNB1/TCF target genes that are activated in the absence of TCF7L1, including EPHB3, a marker of Paneth cell differentiation that has also been implicated as a tumor suppressor in CRC." (PMID 27333864, 2016). "However, it is unclear what function TCF7L1 plays in the development of SCC, and whether its tumor-promoting role requires its interaction with β-catenin." (PMID 28467300, 2017). "In addition, because TCF7L1 overexpression seems to have a paracrine effect on proliferation in vivo and that LCN2 is a secreted protein overexpressed in many types of cancer, we surmise that TCF7L1 may drive tumor growth through induction of LCN2." (PMID 28467300, 2017). "Nevertheless, we could conclude that at least in vitro TCF7L1 is able to override HRAS-induced senescence mainly through its DNA- and Groucho/TLE corepressor binding domains and not on its β-catenin binding domain, similarly to its ability to promote tumor growth." (PMID 28467300, 2017). "Notably, the β-catenin binding-deficient TCF7L1ΔN mutant increased tumor size similarly to full-length TCF7L1, whereas the Groucho/TLE corepressor binding-deficient TCF7L1ΔG did not significantly increase the tumor size (despite having a 100 fold stronger activity on WNT reporter in vitro)." (PMID 28467300, 2017). "Compared with tumor cells at the primary site, metastatic tumor cells still retained high expressions of KRT8 and KRT18, whereas metastatic tumor cells no longer expressed MMRN1, PROX1, TCF7L1, SCG3 and SV2C." (PMID 35494058, 2022). "Remarkably, these pairwise comparisons also reveal that any link to extracellular matrix (ECM) generally excludes TCF7 and TCF7L2, but generally includes both TCF7L1 and LEF1; TCF7L1 more in normal tissue, and LEF1 more in tumor." (PMID 32403323, 2020). "Together, our data therefore imply that TCF7L1 accelerates human SCC cell migration and tumor growth through induction of LCN2 but does not require LCN2 to stimulate neutrophil infiltration." (PMID 28467300, 2017). "Although we do not yet know the direct repressed target genes of TCF7L1 that contribute to skin tumorigenesis, we clearly showed that LCN2 is a major downstream effector of TCF7L1 that drives tumor growth." (PMID 28467300, 2017). "Having observed a reduction in HCT116 cell growth, colony formation, tumor growth, and CSC marker expression in the absence of TCF7L1, we searched for a mechanism to explain this phenotype." (PMID 27333864, 2016).
tumor (continued). "Although TCF7L1 overexpression was not sufficient to promote tumor development without DMBA/TPA, the overexpression of TCF7L1 partially compensated for TPA administration in promoting tumor development, suggesting that TCF7L1 acts as a tumor promoter." (PMID 28467300, 2017). "Since overexpression of TCF7L1* had little effect on tumor size, OIS, and migration while TCF7L1ΔG still affected OIS and SCC cell migration, albeit significantly less than the full length and TCF7L1ΔN, we decided to focus on the genes that were altered by TCF7L1 and TCF7L1ΔN but not by TCF7L1*." (PMID 28467300, 2017). "Since overexpression of TCF7L1 predisposed DMBA/TPA treated skins to develop tumors at a higher rate but did not affect tumor size, it suggests that upregulation of LCN2 by TCF7L1 in the pre-tumor state may be facilitating the transitioning of mutated cells into tumor cells." (PMID 28467300, 2017).
cancer (23 papers, 2012 to 2024). A tumor composed of atypical neoplastic, often pleomorphic cells that invade other tissues. "Among these disease pathways, the upregulated genes were predominantly enriched within the cell proliferation module of cancer-associated pathways, including Lef1, Tcf7l1, and Myc genes." (PMID 39408685, 2024). "Despite a WNT-stimulated cytokine response in the microenvironment being required to maintain aggressiveness and metastatic progression in several types of cancer, there is little knowledge about the upregulation of TCF7L1 associated with cytokine responses in PCa." (PMID 34799554, 2021). "Besides, the expression of TCF7L1 was found to be upregulated in high malignant tumors and was associated with poor survival." (PMID 33824876, 2021). "While efforts have focused on defining the roles of TCF7L2, TCF7, and LEF1 as regulators of Wnt target genes in CRC, the role of TCF7L1 in this cancer is less-well understood." (PMID 38816533, 2024). "Our study further defines a role for TCF7L1 in cancer stem cell biology by demonstrating that TCF7L1 mediates repression of LGR5 expression and that this contributes to reduction of spheroid formation efficiency." (PMID 36833408, 2023). "Silencing of TCF7L1 can significantly inhibit the growth of cancer cells, while overexpression of TCF3 can promote cancer cell proliferation in prostate cancer." (PMID 33824876, 2021). "The transcription factor transcription factor 7-like 1 (TCF7L1) is an embryonic stem cell signature gene that is upregulated in multiple aggressive cancer types, but its role in gastric cancer has seldom been discussed." (PMID 30811526, 2019). "Here we report that TCF7L1 protein is upregulated in premalignant and malignant tumors in both the chemically- and UV-induced mouse models of skin SCC." (PMID 28467300, 2017). "Together, this work supports further investigation in the role of TCF7L1 in other cancer types, particularly those where Wnt signaling is known to regulate normal tissue homeostasis." (PMID 27333864, 2016). "The influence of TCF7L1 has been detected in several types of cancer, such as skin squamous cell carcinoma, colorectal, gastric, and prostate cancers, underscoring its pivotal contribution to the mechanisms of cancer development." (PMID 39608715, 2024). "TCF7L1 may play a specific role in repressing LGR5 expression in a subpopulation of cells to regulate cancer stem cell plasticity." (PMID 36833408, 2023). "It is possible that this repressor function of TCF7L1 may be similarly required in cancers other than skin SCC, but that remains to be determined experimentally in vivo." (PMID 28467300, 2017). "Instead, the Pathways in cancer genes Kras, Met, Figf, Hgf, Fgf7, Ctnnb1 and Tcf7l1, and directly interacting genes Nr3c2 and Csnk2a1 may lead to new insights in US28-mediated signaling and ultimately the oncomodulatory role of HCMV." (PMID 25002203, 2014). "Although TCF7L1 has been ascribed an oncogenic role in CRC, only a few target genes whose expression it regulates have been characterized in this cancer." (PMID 38816533, 2024). "Conversely, the expression levels of transcription factors TCF7L1, TCF7L2 and LEF1 in the Wnt/β-catenin signaling pathway were higher in cancer tissue in both homozygous and heterozygous variation types of the patients." (PMID 29050326, 2017). "Moreover, TCF7L1-mediated upregulation of HSPB6 leads to suppression of the PI3K/AKT/mTOR signaling pathway, a key driver of cancer progression." (PMID 39608715, 2024). "Here, we uncovered the potential involvement of TCF7L1 in cancer metastasis, especially bone metastasis, which was not widely discussed before." (PMID 35127947, 2022). "Our results demonstrated that TCF7L1 promoted gastric cancer cell proliferation by positively regulating aerobic glycolysis and antioxidant response via NRF2, an important player in oncogenesis and progression in many types of cancers." (PMID 30811526, 2019).
cancer (continued). "The transcription factor TCF7L1 is an embryonic stem cell signature gene that is upregulated in multiple aggressive cancer types, but its role in skin tumorigenesis has not yet been defined." (PMID 28467300, 2017). "Among them were CEBPA and CEBPB (cell cycle regulation), RELA and CREL (NF-κB pathway), TCF7L1 (Wnt/β-catenin signaling pathway), SMAD3 [transforming growth factor beta (TGF-β) signaling], FOXO1 and NFAT, all of which are involved in cancer initiation and progression." (PMID 28344555, 2017). "The downregulation of TCF7L1 in BLCA tissues contributes to diminished HSPB6 expression, suggesting that enhancing TCF7L1 activity could serve as a strategic avenue for upregulating HSPB6, thereby potentially inhibiting cancer progression." (PMID 39608715, 2024). "PIK3CA-mutant cancers displayed higher expression of 12 of the 17 Wnt genes compared to PIK3CA wild-type tumors, including five Wnt target genes (LEF1, MYCN, FZD7, SFRP2, and TNFRSF11B) and seven Wnt signaling components (TCF7L1, TCF7L2, CTNNB1, FZD4, SFRP1, WNT5A, and MSX2)." (PMID 34035258, 2021). "We found that the expression levels of the genes in the Wnt/β-catenin signaling pathway, including APC, β-catenin, TCF7L1, TCF7L2, LEF1, MMP7, C-myc, C-jun, CYCLIND1 and GSK-3β, were remarkably higher in cancer than non-cancer tissues in the p.1125Val>Ala mutant FAP family members." (PMID 29050326, 2017).
colorectal (1 paper, 2023). "Incorporation of these models in future work will allow us to better understand how Wnt/β-catenin signaling and TCF7L1 control CRC stem cell populations to promote colorectal carcinogenesis and chemotherapeutic resistance." (PMID 36833408, 2023).
neurodegenerative disease (1 paper, 2025). A disorder of the central nervous system characterized by gradual and progressive loss of neural tissue and neurologic function. "KEGG pathway analysis implicated neurodegenerative diseases pathways and highlighted target genes associated with long-term depression signaling and tryptophan metabolism, including RIN2, TCF7L1, DDIT4, and KLF11." (PMID 41009397, 2025).
TCF7L1 also shares sentences with these, for which no sentence is quoted: glioblastoma (3 papers); breast tumors (2); endometrial cancer (2); gastric cancer (2); glioma (2); leukemia (2); actinic keratosis (1); basal cell carcinoma (1); bone metastasis (1); cardiomyopathy (1); chordoma (1); COVID-19 (1); left ventricular hypertrophy (1); medulloblastoma (1); melanoma (1); psoriasis vulgaris (1); renal carcinoma (1); seborrheic keratosis (1); seminoma (1); skin disorder (1); squamous cell carcinoma (1); testicular seminoma (1); type 2 diabetes (1).